ACO1 (aconitase 1)
Diseases named in the same sentence as ACO1 in open-access papers (continued):
Sharing a sentence is not in itself a finding about the gene and the disease.
tumor (34 papers, 2010 to 2025). "The expression levels of ABCB8 and ACO1 in CM were negatively correlated with the prognostic risk of the tumor." (PMID 38874871, 2024). "After the purity of the tumor was adjusted, ACO1 along with IREB2 expressions was remarkably linked to most immune markers in various kinds of immune cells in KIRC." (PMID 36059676, 2022). "Energy metabolism favours oxidative phosphorylation and the tricarboxylic acid (TCA) cycle (OGDHL, PCK1, ACO1, FH) over glycolysis, limiting tumour growth." (PMID 41007296, 2025). "have demonstrated that knockdown or inhibition of ACO1 expression significantly weakens the anti-tumor and ferroptosis-inducing effects of curcumin." (PMID 39735537, 2024). "The downregulation of ABCB8 and ACO1 can enhance CM cell proliferation, migration and invasion capabilities, thus promoting the development of tumor." (PMID 38874871, 2024). "Meanwhile, ACO1 and IREB2 regulate autophagy-linked ferroptosis along with immune cell invasion in the tumor microenvironment in KIRC patients." (PMID 36059676, 2022). "Regarding the tumor stage, a remarkable decrease in ACO1 and IREB2 expression was watched in KIRC patients in stages I, II, III, and IV." (PMID 36059676, 2022). "We found that Notch3-silenced tumours have significant lower levels of Aco1, Idh1 and Mdh1 than control counterparts." (PMID 30765875, 2019). "In different tumor stages, low ACO1 expression was accompanied with worse OS, DSS, and PFI only in stage 1 and 3 patients with KIRC, while low IREB2 expression was strongly accompanied with worse OS in stage 1,worse DSS in stage 3, and worse PFI in stage 1 and 3 patients with KIRC." (PMID 36059676, 2022). "Additionally, as tumor stages and distant metastasis progressed, ACO1 coupled with IREB2 contents decreased." (PMID 36059676, 2022). "To assay whether Notch3-mediated regulation of Mdh1, Idh1 and Aco1 protein expression really occurs in primary tumours, we examined protein abundance in Notch3-silenced and control rats after brivanib treatment." (PMID 30765875, 2019). "The immunohistochemistry images from The HPA database showed that ACO1 and GOT1 levels were lower in tumor compared to normal tissues." (PMID 36733386, 2022). "When using the TIMER data resource, we noticed that the ACO1 and IREB2 contents were strongly accompanied with 33 of 38 T-cell biomarkers in KIRC after adjusting for tumor purity." (PMID 36059676, 2022). "We assessed the links between ACO1 and IREB2 and immune invasion by using the accomplished data resource CIBERSORT, which reflects the influences of ACO1 and IREB2 on the tumor microenvironment (TME)." (PMID 36059676, 2022). "The gene expressions of AOC1 (P < 0.001), FDX1 (P = 0.003), MT-CO1 (P < 0.001), and ACO1 (P < 0.001) in HCC tumor tissues were remarkably lower than those in normal tissues." (PMID 36313717, 2022). "Insufficiently, the tangible role of ACO1 and IREB2 in the tumor-immune microenvironment still requires further in-depth investigation." (PMID 36059676, 2022). "Still, further research into the apparent modulatory mechanisms along the functions of ACO1, IREB2 in tumor proliferation, metastasis, and immunological invasion is required." (PMID 36059676, 2022). "The heatmap showed that more than half of the genes were downregulated in tumor tissue, and consistent with the univariate Cox regression analysis, they represented a better prognosis, including PTGS2, ACO1, DPP4, CRYAB, PRKCA, ACSL4 and AKR1C3." (PMID 34475496, 2021). "In Muc2 IECs, the data document decreased expression of Aconitase 1 (Aco1), and concomitant elevation of Acly, thus, increasing ATP-citrate-lyase (ACL)-dependent production of acetyl-CoA important for the proliferation of tumor cells and lipogenesis." (PMID 29069719, 2017). "PC, ACO1, IDH2 and PCK1 and were overexpressed in tumor samples from liver metastases only." (PMID 22412968, 2012).
tumor (continued). "The result suggested ACO1 was a negative contributor of tumor grade, and increasing the ACO1 expression may play the protective role of tumor grade." (PMID 35154262, 2021).
cancer (26 papers, 2010 to 2025). A tumor composed of atypical neoplastic, often pleomorphic cells that invade other tissues. "Slowing the ACO1 vitality decreased the capability of T-cell lymphoblastic neoplasia cells, and ACO1 knockdown makes resistant cell lines susceptible to fluorocitrate, which represented that ACO1 is a new powerful therapeutic strategy for the healing of diverse cancers." (PMID 36059676, 2022). "Here, we identify cancer cells selectively secrete miR-33a with the assistance of aconitase 1 (ACO1), an iron-responsive RNA binding protein, under glucose starvation and lower iron level, which affiliates the binding capability of miR-33a and ACO1." (PMID 40903826, 2025). "ENO1, as an RNA-binding protein, can accelerate the messenger RNA decay of ACO1 in cancer cells, leading to repression of ferroptosis." (PMID 37492576, 2023). "Inhibition of the CS activity or knockdown of ACO1 blocks the rescue effect of inosine on cancer survival under starvation." (PMID 37532694, 2023). "In the diversity of cancers, the ACO1 locus on chromosome 9p21.1 and IREB2 locus on chromosome 15q25.1 are generally deleted." (PMID 36059676, 2022). "Some studies showed the ectopic overexpression of ACO1 and IRP1 in some types of cancer." (PMID 37108831, 2023). "In current research, the phenomenon that ACO1 and IREB2 are involved in numerous cascades were revealed in GO along with the KEGG pathway enrichment analyses of ACO1, IREB2 and the linked genes, especially the PD-L1 expression state and PD-1 checkpoint cascade in cancer." (PMID 36059676, 2022). "Therefore, ACO1 and IREB2 can work as independent risk factors and prognostic biomarkers of several types of cancer." (PMID 36059676, 2022). "Although paralogous synthetic lethal pairs like STAG1/STAG2 and IREB2/ACO1 are interesting biologically, how the large therapeutic window of these paralogous synthetic lethal interactions can be translated into potential cancer therapeutics is an open question." (PMID 34462321, 2021). "Considering the expression level of ACO1 and IREB2 were closely related to progression and metastasis in KIRC patients, we then assessed their value in cancer prognosis." (PMID 36059676, 2022). "Cytoplasmic aconitate hydratase (ACO1) is a protein involved in cytoplasmic and mitochondrial metabolism that when downregulated leads to cell death, potentially representing a new therapeutic strategy for cancer treatment." (PMID 32841536, 2020). "Whether IDH1/2 follows a similar strategy to ACO1 or TYMS, and whether it plays key roles in cancer development will be important to explore." (PMID 29216518, 2018). "Moreover, lipocalin 2 (LCN2) inhibits ferroptosis by limiting iron uptake, while aconitase 1 (ACO1, also known as IRP1) and iron responsive element binding protein 2 (IREB2, also known as IRP2) promote ferroptosis in cancer cells by regulating the translation of iron metabolism-related protein." (PMID 34742351, 2021).
infection (21 papers, 2010 to 2024). The state of being infected such as from the introduction of a foreign agent such as serum, vaccine, antigenic substance or organism. "This is evident especially for ACO5, which contrary to ACO1, showed downregulation of gene expression at both of the analyzed time points upon Cmm infection." (PMID 34445148, 2021). "Interestingly, a subset of identified genes associated with ethylene synthesis and response, including ACO1, ACO5, Pr4 and Pr6, were also reported in a previous tomato microarray analysis upon Cmm infection." (PMID 34445148, 2021). "1-aminocyclopropane-1-carboxylic acid oxidase genes (ACO4 and ACO1) and ACC synthase genes (ACS2, ACS6 and ACS7) encoding proteins involved in ET biosynthesis, and ERF1, PR3 and PR4, which are induced by treatment with JA or ET, were all upregulated during infection (cluster VII)." (PMID 29281727, 2017). "We then assessed the mRNA levels of four genes (PTI5, ACO1, OPR3 and PR-1), whose expression reflects the activation of different defense and stress pathways, at the early stages of infection (16 hours after inoculation)." (PMID 29377937, 2018). "Four of the identified genes, aco-1, cct-2, daf-19 and hsp-60, were knocked down using RNAi and ACO-1, CCT-2 and DAF-19, which were identified as up-regulated in response to S. flexneri infection, were found to be involved in the infection process." (PMID 25187942, 2014). "Moreover, a decreased expression of enzyme subunits (MDH2 and SUCLA2) and an elevated expression of ACO1 and SUCLG2 in the cycle were observed post infection." (PMID 37256871, 2023). "Surpass400 – H75 8-1 and 01-23-2-1 displayed late up-regulation of ACO1 (i.e., 7 and 11 dpi) whilst Westar did not have apparent activation throughout infection." (PMID 33946839, 2021). "The Lox1.1 gene was strongly downregulated by the infection with B. cinerea, whereas PGIP and Aco1 genes were significantly upregulated, irrespective of the treatment with S. rhizophila." (PMID 37849842, 2023).
ACO1 also shares sentences with these, for which no sentence is quoted: pulmonary hypertension (7 papers); Iron overload (3); liver cancer (3); pancreatic cancer (3); prostate carcinoma (3); Alzheimer disease (2); colitis (2); endometrial carcinoma (2); Friedreich ataxia (2); Liver abscess (2); microcytic anemia (2); neuroblastoma (2); non-small cell lung carcinoma (2); Obesity (2); pheochromocytoma (2); respiratory infection (2); Respiratory tract infection (2); viral infections (2); amyloidosis (1); autism (1); bacteremia (1); brain cancer (1); cardiac hypertrophy (1); cervical cancer (1); cholangiocarcinoma (1); cholestasis (1); colon adenocarcinoma (1); colon tumor (1); colorectal adenocarcinoma (1); Down syndrome (1).
A further 39 diseases each share a sentence with ACO1 in 1 paper.